MAFG (MAF bZIP transcription factor G)
Diseases named in the same sentence as MAFG in open-access papers (continued):
Sharing a sentence is not in itself a finding about the gene and the disease.
choroidal melanoma (1 paper, 2025). Malignant tumor of melanocytes of the choroid. "In conclusion, comprehensive in vivo and in vitro experiments, coupled with clinical sample analysis, confirm that the MAFG-METTL14-SCD1 axis promotes choroidal melanoma cell metastasis by modulating cardiolipin and fatty acid pathways." (PMID 41316357, 2025). "We demonstrated for the first time that MAFG is highly expressed in choroidal melanoma." (PMID 41316357, 2025). "Our novel findings further highlight the direct binding of MAFG to METTL14, revealing that MAFG specifically binds to the promoter region of METTL14, and its heightened expression in choroidal melanoma is dependent on MAFG’s recognition of a critical motif, which triggers its specific activation." (PMID 41316357, 2025).
colon adenocarcinoma (1 paper, 2020). "This is evidenced by the recent finding that BRAF V600E and KRAS G13D mutations in colon adenocarcinoma upregulate the transcription factors MAFG and ZNF304, respectively, resulting in targeted promoter CGI hypermethylation near the MAFG and ZNF304 binding sites." (PMID 32327612, 2020).
COVID-19 (1 paper, 2021). A disease caused by infection with severe acute respiratory syndrome coronavirus 2. "Interestingly, although with a lesser intensity, the upregulation of AREG, MAFG, MAFK, BCL6 and IL10 still persisted in monocytes of post-COVID-19 subjects." (PMID 34572439, 2021).
glioma (1 paper, 2020). A benign or malignant brain and spinal cord tumor that arises from glial cells (astrocytes, oligodendrocytes, ependymal cells). "We showed that XL388 downregulated MAFG and inhibited Nrf2 signaling, causing significant ROS production and oxidative injury in glioma cells." (PMID 33159013, 2020). "XL388 downregulated MAF bZIP transcription factor G (MAFG) and inhibited Nrf2 signaling, causing oxidative injury in glioma cells." (PMID 33159013, 2020). "Here we will show that XL388 downregulated MAFG, causing Nrf2 signaling inhibition and ROS production in glioma cells." (PMID 33159013, 2020). "In A172 glioma cells, MAFG mRNA expression was significantly downregulated following XL388 treatment." (PMID 33159013, 2020). "Indeed, we show that MAFG-Nrf2 inhibition could be another mechanism for XL388-induced actions in glioma cells." (PMID 33159013, 2020).
Glucose intolerance (1 paper, 2020). Glucose intolerance (GI) can be defined as dysglycemia that comprises both prediabetes and diabetes. "Intriguingly though, driving Mafg, alone or coupled to LincIRS2 loss, again caused glucose intolerance to similar extents, arguing for synergistic roles of MAFG overexpression and LincIRS2 deletion in glucose metabolism." (PMID 32005828, 2020).
Hypercholesterolemia (1 paper, 2021). An increased concentration of cholesterol in the blood. "Our results also demonstrate that MAFG might be the primary target that mediates the effect of hepatic miR-378 on BA and cholesterol metabolism, while miR-378 and MAFG could serve as therapeutic targets for the treatment of hypercholesterolemia." (PMID 33754066, 2021).
liver cancer (1 paper, 2021). An epithelial or non-epithelial malignant neoplasm that arises from the liver. "Oncogenic roles for MAFG have so far been described in lung, ovarian, colorectal, and liver cancer." (PMID 33808771, 2021).
oral cancer (1 paper, 2023). "We report the molecular docking analysis for oral cancer drug, Imiquimod with TGF-β signaling pathway targets such as Smad2, GATA2, and MAFG which are mainly plays a crucial role in regulation of Epithelial Mesenchymal Transition(EMT) in cancer cells." (PMID 37822834, 2023).
oral squamous cell carcinoma (1 paper, 2023). "The lncRNAs MAFG-AS1, lncRNA EIF3J-AS1 and LINC00284 upregulate MafG to promote proliferation and metastasis and inhibit apoptosis by sponging miR-744-5p and miR-211-3p in lung adenocarcinoma, prostate cancer and oral squamous cell carcinoma." (PMID 36750911, 2023).
osteosarcoma (1 paper, 2021). A usually aggressive malignant bone-forming mesenchymal neoplasm, predominantly affecting adolescents and young adults. "A novel microRNA, miR-4660, selectively silenced MAFG to inhibit osteosarcoma cell progression in vitro and in vivo." (PMID 33868783, 2021). "MAFG overexpression is involved in osteosarcoma tumorigenesis and progression." (PMID 33868783, 2021).
ovarian carcinoma (1 paper, 2020). A malignant neoplasm originating from the surface ovarian epithelium. "One of the effects of miR-7 silencing in cisplatin-resistant lung and ovarian cancer cell lines is the upregulation of its target gene MAFG (Musculoaponeurotic Fibrosarcoma Oncogene Family, protein G)." (PMID 32492865, 2020). "An example of this is the miR-7/MAFG axis regulation in NSCLC and ovarian cancer." (PMID 32492865, 2020).
sarcoma (1 paper, 2021). A usually aggressive malignant neoplasm of the soft tissue or bone. "As shown, in children’s sarcoma tissue (n = 1,524) MAFG mRNA expression is significantly upregulated (p < 0.05 versus normal tissues; n = 66)." (PMID 33868783, 2021). "Furthermore, MAFG mRNA upregulation is detected in 14 cases of recurrent children’s sarcoma samples." (PMID 33868783, 2021). "To examine MAFG expression in OS, we first consulted the TARGET Pan-Cancer (PANCAN) database to examine RNA sequencing (RNA-seq) data in children’s sarcoma tissues and normal adjacent tissues via a UCSC Xena project." (PMID 33868783, 2021).
tumor (28 papers, 2012 to 2025). "This mirrors past studies showing NFE2L1/MAFG promotes PD‐L1 via super enhancers and LPS, facilitating tumor immune escape." (PMID 40677211, 2025). "Numerous studies have clearly established the central role of the transcription factor MAFG in tumor invasion and metastasis." (PMID 41316357, 2025). "To validate our findings, we employed Kaplan-Meier survival curves and ROC curves to analyze the key genes associated with C2 tumor cell subtypes, including the top five transcription factors (IGF2, PRRX1, MAFB, LBX2, GATA2, MAFG)." (PMID 39896800, 2024). "Together, these results suggest that YAP phosphorylation relieves the repression of MAFG and β8 genes, thus promoting stemness gene expression and forming a mechano-regulatory loop for tumor cell dedifferentiation." (PMID 37614365, 2023). "We found that fibrinogen levels were positively correlated with MAFG expression and the tumor pathological grade." (PMID 37614365, 2023). "Identification of the regulation of tumor cell dedifferentiation by the β8-RhoGDI1-RhoA-YAP-MAFG mechanical signaling pathway prompted us to validate the potential translation of MAFG in cancer patients." (PMID 37614365, 2023). "MAFG also can play a role as a molecular biomarker for tumor-targeted therapy to relieve cisplatin resistance of tumor cancer cells, improving therapeutic and prognostic efficiency." (PMID 36226171, 2022). "Among those, SLC2A12, TXNIP, and MAFG were found to have low expressions in the tumor tissue samples, while the others were highly expressed." (PMID 34386423, 2021). "The tumor growth curve results confirmed that tumors bearing MAFG shRNA or lv-pre-miR-4660 grew significantly slower than the control tumors." (PMID 33868783, 2021). "The estimated daily tumor growth, calculated by the formulation (tumor volume at day 42 − tumor volume at day 0)/42, confirmed that MAFG shRNA or miR-4660 overexpression robustly inhibited pOS-1 xenograft growth in SCID mice." (PMID 33868783, 2021). "An example of this is the miR-7/MAFG/ROS axis that leads to cellular and biological responses that promote tumor development and progression in different tumor types." (PMID 32492865, 2020). "In addition, we found that NLS-YAP or NES-YAP markedly downregulated or upregulated MAFG expression in soft fibrin gel-cultured tumor cells." (PMID 37614365, 2023). "In addition, MAFG overexpression upregulated stemness genes in the rigid-plate-cultured tumor cells." (PMID 37614365, 2023). "The insignificant difference of MAFG expression between tumor and normal tissues may be attributed to the antibody specificity." (PMID 36685838, 2022). "miR-4660 expression was unchanged in MAFG shRNA-expressing tumor tissues." (PMID 33868783, 2021). "However, not all CIMP-H tumours carry this mutation, suggesting either MAFG activity is increased via a different mutation or an alternative mechanism of hypermethylation exists in CIMP-H tumours." (PMID 28351398, 2017). "Two GRNs, albeit comprising a smaller number of tumor cells, showed high activity for the TCF7L2 regulon (along with KLF8, FOXK1, FOXP2, and BACH1) (labeled TCF7L2+) and CTCF (along with MAFG and NR1H) (labeled CTCF+), respectively." (PMID 38968122, 2024). "Two GRNs, albeit comprising a smaller number of tumor cells, showed high activity for the TCF7L2 regulon (along with KLF8, FOXK1, FOXP2, BACH1) (labeled TCF7L2+) and CTCF (along with MAFG and NR1H) (labeled CTCF+) respectively." (PMID 38645034, 2024). "Our study confirmed MAFG overexpression both in mRNA and protein levels in HCC, and its promoting role for advanced tumor grade, TNM stage, tumor invasion and dismal prognosis in HCC patients." (PMID 36685838, 2022). "It has been shown that Bach1 can form a complex with MAFG and the DNA methyltransferase DNMT3B, which resulted in the repression of tumor suppressor genes." (PMID 34949193, 2021).
tumor (continued). "Furthermore, MAFG seems to be leading a methylator program of specific genes in colorectal and melanoma cancer, so that its increase could affect the methylation profile of different tumor suppressor genes, promoting the cancer cell survival." (PMID 32492865, 2020). "Remarkably, MAT1A overexpression, or c-MYC, MAFG, or c-MAF inhibition in tumor cells dramatically inhibited their in vitro and in vivo growth." (PMID 28422055, 2017). "By contrast, up-regulation of c-MYC, MAFG, and c-MAF or attenuation of MATa1 expression by knock-down triggered increased tumor cell growth and invasion in vivo." (PMID 28422055, 2017). "Two genes, MAFG and FECH were significantly upregulated in five and four tumour types, respectively, in the presence of NFE2L2 aberrations (FDR<0.1)." (PMID 26436532, 2015). "However, in the bulk-seq data of tumor tissues from TCGA-LIHC, MAFG (69.16%) had a greater mediating effect than HES4 (17.08%), possibly because of the higher distribution of MAFG in nonmalignant cells." (PMID 39616302, 2024). "We found that the knockdown of RUNX2 but not TEAD or P73 upregulated the expression of MAFG and stemness genes in stiff tumor cells." (PMID 37614365, 2023). "This study is advantaged at the identification and validation of a novel 2-TF signature consisted of HMGA1 and MAFG, which is able to predict the prognosis and therapeutic response of HCC via distinguishing the characteristics of tumor proliferation and metabolism." (PMID 36685838, 2022). "Additionally, an increased interaction between MAFG and NRF2 was previously observed upon tumor exposure to the kinase inhibitor of sorafenib, whereas NRF2 inhibition promoted the response to sorafenib in HCC." (PMID 36685838, 2022).
cancer (20 papers, 2010 to 2025). A tumor composed of atypical neoplastic, often pleomorphic cells that invade other tissues. "These docking results suggests a significant association of binding affinities between the interaction of Imiquimod and TGF-βbeta; signaling targets (Smad2, GATA2, and MAFG) which are mainly involved in the metastaticproperty in cancer cells." (PMID 37822834, 2023). "To further support these conclusions, we analyzed the cancer cell line database across all members of the NFE2:MAF family including MAFG, MAFF, MAFK, NFE2L1, and NFE2L2." (PMID 37985752, 2023). "Taken together, our results demonstrate the critical role of locus 22, NFE2L1, and MAFG in helping cancer cells evade T-cell killing by upregulating super-enhancer–mediated PD-L1 expression." (PMID 37985752, 2023). "Although the function of NFE2L1/2 and its binding partners (MafG, MafF, and MafK) to form heterodimers in cancer has been extensively studied, their distinguishing roles in the regulation of PD-L1 and immune evasion are poorly understood." (PMID 37985752, 2023). "MAF BZIP transcription factor G (MafG) interacts with methionine adenosyltransferase a1 to regulate transcription; MafG is overexpressed in cancer cells." (PMID 34828279, 2021). "Since TWEAK-mediated non-canonical NF-κB activation and the cooperativity of NF-κB/p52 with non-κB factors have been documented in cancer cells, we hypothesised the possibility of p52 facilitating MAFG recruitment to enhancer sites following TWEAK treatment." (PMID 38965263, 2024). "Using The Cancer Genome Atlas (TCGA) and Gene Expression Omnibus (GEO) databases of RNA sequencing (RNA-seq) data, we found that MAFG expression was negatively correlated with BRCA and SKCM patient survival, which also had a positive correlation with the stemness score of the tumors." (PMID 37614365, 2023). "In this study, we found that MAFG could promote cell proliferation and metastasis in PCa, and downregulating MAFG can impair the cancer-promoting effects of EIF3J-AS1 in PCa." (PMID 34976178, 2022). "However, there are a number of reports that relate the overexpression of MAFG to cancer development and progression." (PMID 32492865, 2020). "MAFG silencing increased ROS production to sensitize cancer cells cisplatin." (PMID 33159013, 2020). "The GG genotype was associated with the “without cancer” status of smokers (p = 0.0199), and also marginally with the higher expression level of MAFG." (PMID 20689807, 2010). "Accumulating evidence has demonstrated the oncogenic roles of EREG, MAFG and GAS6 in various cancers." (PMID 40819060, 2025). "To evaluate the role of MAFG in mediating TWEAK-driven NAMPT expression, we found a significant positive correlation between MAFG and NAMPT expression in the TCGA BRCA and Pan-cancer dataset." (PMID 38965263, 2024). "This is consistent with our knowledge that, in this type of cancer, BRAF V600E recruits DNA methyltransferase to CGI targets by stimulating the MEK/ERK signaling pathway and upregulating the transcription repressor MAFG." (PMID 29125844, 2017). "Notably, the MAFG probe-set 204970_s_at was associated with “without cancer” status (p = 0.0014)." (PMID 20689807, 2010). "Dysregulation of MafG has been identified by proteomic profiling in highly metastatic cancer cells relative to nonmetastatic cancer cells." (PMID 36750911, 2023). "Although the p-value was not less than 0.05, we found that MAFG with VDAC2 presented higher expression in paracancerous tissues than in cancer tissues, and TXNIP presented lower expression in paracancerous tissues than in cancer tissues." (PMID 34869576, 2021).
metabolic disease (1 paper, 2020). A congenital disorder (due to inherited enzyme abnormality) or acquired (due to failure of a metabolically important organ) disorder resulting from an abnormal metabolic process. "Taken together, we identify a MAFG-lncRNA axis controlling hepatic glucose metabolism in health and metabolic disease." (PMID 32005828, 2020).
MAFG also shares sentences with these, for which no sentence is quoted: cholestasis (2 papers); infection (2); multiple sclerosis (2); Ataxia (1); Barrett esophagus (1); bladder cancer (1); brain tumor (1); cataract (1); co-infection (1); Diabetic Foot Ulcers (1); esophageal cancer (1); hepatitis B (1); Insulin resistance (1); lung adenocarcinoma (1); lung squamous cell carcinoma (1); Multiple Organ Failure (1); skin cancer (1); spinal cord injury (1); type 2 diabetes (1); uterine corpus endometrial carcinoma (1); vitiligo (1).